EGFR (epidermal growth factor receptor)
Diseases named in the same sentence as EGFR in open-access papers (continued):
Sharing a sentence is not in itself a finding about the gene and the disease.
head and neck cancer (continued). "Our data are in line with previous studies showing that EGFR mutated tumors display an uninflamed phenotype and that cetuximab treatment may lead to increased T-cell infiltration in head and neck cancers." (PMID 30192802, 2018). "EGFR is also broadly expressed in head and neck cancer and has been linked to patient survival." (PMID 29464041, 2018). "When samples overexpressing EGFR variants 1 and 3 included samples with both high and moderate-levels of genomic amplification, samples in which both EGFR variants were overexpressed with genomic amplification were abundant in lung, and head and neck cancer samples." (PMID 28377632, 2017). "Further, loss of E-cadherin could promote proliferation of head and neck cancer cells through activating epidermal growth factor receptor (EGFR) pathways." (PMID 22645613, 2012). "Post-translational regulation of TWIST1 might also be mediated through mutated EGFR activation, indeed, in head and neck cancer, IL6 activation was recently shown to stabilize TWIST1 through CK2 phosphorylation." (PMID 22272264, 2012). "Consequently, EGFR overexpression in many tumors, such as head and neck carcinomas, is associated with malignancy and more aggressive phenotypes." (PMID 22623992, 2012). "Mutant EGFR, a truncated EGFR variant (EGFRvIII), has also been described in head and neck cancer." (PMID 21958730, 2011). "The primary causative factor for lung and head and neck cancer is smoking, and both possess similar molecular characteristics which have been implicated in the pathogenesis of disease, such as a key role of the human epidermal growth factor receptor (EGFR) in tumor growth." (PMID 23405260, 2013). "It details how EGFR inhibition affects tumor progression and survival in head and neck cancer, noting that small molecule inhibitors and monoclonal antibodies, such as cetuximab, can lead to trans-activation of other RTKs." (PMID 40560045, 2025). "At last, CSM 3 was modified with a small protein anti-epidermal growth factor receptor (EGFR) affibody (CSM 3-affibody) for early-stage detection of head and neck cancers in which EGFR was overexpressed." (PMID 39801503, 2025). "In head and neck cancer, a major concern regarding targeted therapy is resistance to anti-EGFR based therapies despite high levels of EGFR expression." (PMID 40560045, 2025). "For instance, anti-epidermal growth factor receptor (EGFR)-targeted NIR-PIT is approved in Japan for advanced head and neck cancers which typically express EGFR on cancer cells." (PMID 41410776, 2025). "Oral cancer, one of the subtypes of head and neck cancer, has typical hypoxic characteristics and abnormal EGFR activation." (PMID 40940319, 2025). "Erlotinib is a first-generation TKI targeting EGFR, and miR-7 is a miRNA that acts as adjuvant with erlotinib in head and neck cancer." (PMID 40283927, 2025). "In this report, we aim to review RTK signaling pathways using breast and head and neck cancer as model systems, given their relatively high levels of EGFR expression." (PMID 40560045, 2025). "For example, EGFR activation, which is commonly observed in head and neck cancer, promotes tyrosine phosphorylation of MOB1 and subsequently inhibits LATS1/2 activity." (PMID 40486910, 2025). "Cetuximab, a chimeric human-mouse mAb targeting the epidermal growth factor receptor (EGFR), is approved for the treatment of colorectal and head and neck cancers." (PMID 41586193, 2025). "Epidermal Growth Factor Receptor (EGFR) targeted therapies have yielded variable results in clinical trials for breast and head and neck cancers, despite EGFR overexpression in these malignancies." (PMID 40560045, 2025). "Understanding these non-RTK-mediated mechanisms of resistance is crucial for developing effective strategies to overcome resistance to EGFR-inhibiting treatments in head and neck cancer." (PMID 40560045, 2025).
head and neck cancer (continued). "The first clinical application of NIR-PIT uses an anti-epidermal growth factor receptor (EGFR) antibody conjugated to IR700 in patients with head and neck cancer." (PMID 39751657, 2025). "Epidermal growth factor receptor (EGFR) inhibitors have been the only significant advancement in pharmacological treatment for head and neck cancers over the past few decades." (PMID 40296914, 2025). "Although cetuximab, an EGFR inhibitor, can enhance radiation’s effects, it has shown inferior overall survival compared to cisplatin in certain head and neck cancers." (PMID 40429363, 2025). "In a clinical context, a global Phase 3 trial of ASP‐1929, an anti‐epidermal growth factor receptor (EGFR) antibody IR700 conjugate for recurrent or inoperable head and neck cancer patients, is currently ongoing (NCT03769506)." (PMID 40830817, 2025). "Here, paired-agent imaging (PAI) is used to dynamicallytrack the availability of the epidermal growth factor receptor (EGFR)in response to in vivo ligand or inhibitor bindingin individual mice with head and neck cancer (HNC)." (PMID 40367338, 2025). "This review highlights the role of AXL, MET, and RON families of RTKs in tumor progression and resistance to anti-EGFR therapies, focusing on breast and head and neck cancers." (PMID 40560045, 2025). "Adding gastrin-releasing peptide (GRP) to head and neck cancer cells increases the tyrosine phosphorylation of the EGFR within minutes in a Src-dependent mechanism." (PMID 41007372, 2025). "The most important target for treatment strategies in head and neck cancers is the epidermal growth factor receptor (EGFR)." (PMID 39857992, 2025). "Preclinical studies have shown that EGFR plays a radioprotective role in head and neck cancer, leading to decreased effectiveness in response to ionizing radiation." (PMID 40560045, 2025). "NIR‐PIT targeting EGFR has been approved in Japan for patients with advanced head and neck cancer, who have previously received radiotherapy, and has shown good therapeutic effects in clinical practice." (PMID 38888415, 2024). "Further, EGFR-targeted PIT using IRDye700-cetuximab conjugates is in phase III clinical trials for recurrent head and neck cancer patients (NCT03769506, ASP-1929), with early conditional approval in Japan." (PMID 39261715, 2024). "In head and neck cancer models, liposome-mediated plasmids have been used to target specific molecules such as the epidermal growth factor receptor (EGFR)." (PMID 39469621, 2024). "One potential approach is to combine bufalin with Cetuximab, an FDA-approved monoclonal antibody targeting EGFR, widely used in treating head and neck cancers." (PMID 39123466, 2024). "Typical target molecules, such as epidermal growth factor receptor (EGFR), human epidermal growth factor receptor type 2 (HER2), fibroblast growth factor receptor (FGFR), are mutated or amplified in only about 20% of head and neck cancers." (PMID 38978333, 2024). "Currently, NIR-PIT targeting epidermal growth factor receptor (EGFR) with an mAb–IR700Dye conjugate is under global phase III clinical evaluation for the treatment of head and neck cancers (NCT03769506)." (PMID 38542206, 2024). "An analysis of the gene expression profile of head and neck cancer found that a phenotype called the basal type, in which gene expression of the pathway related to EGFR is activated, is particularly common in oral cancer." (PMID 39011480, 2024). "Currently, a phase III clinical trial is underway in patients with head and neck cancer utilizing cetuximab-IR700 (Cet-IR700) to target the epidermal growth factor receptor (EGFR)." (PMID 38475023, 2024). "The simultaneous targeting of ITGB1 and EGFR also produced radio-sensitizing effects on head and neck cancer, aIIB2 increased cytotoxicity and radio-sensitization in a variety of head and neck cancer cells when combined with cetuximab and X-rays." (PMID 38279122, 2024).
head and neck cancer (continued). "Acneiform eruptions were reported in patients affected by lung, colorectal, or head and neck cancers and treated with EGFR-inhibitors." (PMID 38510242, 2024). "Resistance to cetuximab (anti-EGFR) in head and neck cancer and oral squamous cell carcinoma has been observed because of EMT transition and loss of EGFR expression was also noticed." (PMID 38216921, 2024). "There are other potential biomarkers that have been studied in head and neck cancer, including EGFR, KRAS, PIK3CA, and p16INK4a protein." (PMID 36980171, 2023). "A recent study showed that overexpression of EGFR can mediate the immune escape of tumor cells by upregulating PD-L1 expression in head and neck cancers." (PMID 36812484, 2023). "Immune biomarker modulation was observed in an phase Ib clinical trial of patients with head and neck cancer treated with neoadjuvant cetuximab, an epidermal growth factor receptor (EGFR)-specific antibody, plus CD137 agonist urelumab." (PMID 37475035, 2023). "Several immunotherapy agents have been approved for treating head and neck cancer, including antibodies targeting EGFR and immune checkpoint inhibitors for managing recurrent or metastatic tumors." (PMID 37046740, 2023). "One of the most explored targets in the field of fluorescence-guided surgery is the epidermal growth factor receptor (EGFR), as it is overexpressed in several types of cancer, including breast, lung, bladder, brain, and head and neck cancer." (PMID 37781693, 2023). "have reported that compared with EGFR single inhibition, the combination of integrin β1 and EGFR targeting resulted in enhanced cytotoxicity and radiosensitization of head and neck cancer cells, which responded with FAK dephosphorylation." (PMID 37932738, 2023). "Cetuximab, a chimeric mouse/human monoclonal antibody, is an Epidermal Growth Factor Receptor (EGFR) inhibitor developed in the early 2000s for the treatment of patients with metastatic colorectal or head and neck cancer." (PMID 36624467, 2023). "The use of CD137 agonist mAb urelumab also enhanced cetuximab (anti-EGFR)-activated NK-cell survival, DC maturation, and tumour antigen cross-presentation in patients with head and neck cancer." (PMID 36980527, 2023). "For head and neck cancers, these include epidermal growth factor receptor (EGFR) inhibitors and immune checkpoint inhibitors targeting programmed death 1 (PD-1) and programmed death ligand 1 (PD-L1)." (PMID 37760517, 2023). "TKIs, which target EGFR, have proven to be highly effective in treating some of the most common and difficult cancers, including lung, colon, breast, head and neck cancers." (PMID 36768973, 2023). "EGFR, which is overexpressed in esophageal, lung, and head and neck cancers, induced metastasis by Src-STAT signaling." (PMID 38201459, 2023). "The epidermal growth factor receptor (EGFR) is overexpressed in many neoplastic cells, including head and neck cancer." (PMID 36902321, 2023). "EGFR is overexpressed in over 90% of head and neck cancers, and that results in patients living shorter lives." (PMID 36768973, 2023). "We recently reported a similar downregulation of EGFR and ErbB2 levels in Bor-treated head and neck carcinoma cells." (PMID 37069690, 2023). "A phase II clinical trial in which anti-NKG2A was combined with an epidermal growth factor receptor inhibitor in previously treated head and neck carcinomas showed a 31% objective response rate." (PMID 37809084, 2023). "The treatment of TNBC, metastatic lung, colon, pancreas and head & neck cancers with epidermal growth factor receptor (EGFR) inhibitors leads to multi drug resistance (MDR) in the patients." (PMID 36241668, 2022). "Resistance to EGFR-targeted therapy is a major obstacle on the road to effective treatment options for head and neck cancers." (PMID 36551613, 2022). "Several additional associations correspond to dependencies on upstream regulators of cancer genes such as MDM2 in skin and kidney cancers and EGFR in head and neck cancer." (PMID 35382456, 2022).
head and neck cancer (continued). "In head and neck cancer, loss of PTPRS promoted EGFR activity in the EGFR/phosphoinositide 3 kinase (PI3K) pathway." (PMID 35991009, 2022). "An anti-epidermal growth factor receptor (EGFR) antibody panitumumab conjugated to a NIR dye is under investigation and has been used in resection of head and neck cancers that express EGFR." (PMID 35565350, 2022). "n recent years, anti-EGFR Mabs such as cetuximab and nimotuzumab were applied as a concomitant therapy with radiation therapy for head and neck cancer." (PMID 36741709, 2022). "In head and neck cancers, inertia features showed a correlation with epidermal growth factor receptor (EGFR)." (PMID 35340222, 2022). "Honokiol (HON) inhibits epidermal growth factor receptor (EGFR) signaling and increases the activity of erlotinib, an EGFR inhibitor, in human head and neck cancers." (PMID 36601474, 2022). "Cetuximab (C225, Erbitux), a chimeric human/murine IgG1 mAb that targets the epidermal growth factor receptor (EGFR/ErbB1), is indicated for the treatment of patients with colorectal and head and neck cancer." (PMID 35745604, 2022). "EGFR monoclonal antibodies are now standard-of-care therapies for head and neck cancer and colorectal cancer." (PMID 35840984, 2022). "Again, EGFR stands out as being a highly connected protein node in the solution networks for both the brain cancer and head and neck cancer data sets." (PMID 35338126, 2022). "EGFR upregulation is an established biomarker of treatment resistance and aggressiveness in head and neck cancers (HNSCC)." (PMID 36333293, 2022). "For examples, epidermal growth factor receptor (EGFR) is commonly overexpressed in head and neck cancer and thus the anti-EGFR therapeutics are used for the patients with head and neck cancer." (PMID 35207629, 2022). "We confirmed the reactivity and cytotoxicity of EGFR-specific HTLs against tumor cell lines and the presence of EGFR-specific HTLs in head and neck cancer patients, suggesting that self-antigen-reactive T-cells exist and can recognize tumors." (PMID 35062731, 2022). "Emerging individual targets include PTPRZ1 for brain and head and neck cancers and EGFR in multiple tumor types." (PMID 35338126, 2022). "For decades, the epidermal growth factor receptor (EGFR) inhibitor cetuximab remained the only targeted drug approved for head-and-neck cancers." (PMID 36143308, 2022). "As a matter of fact, EGFR amplification is prevalent in many tumor types, including head and neck cancer." (PMID 35806120, 2022). "To this end, we used the MOC2 mouse head and neck carcinoma cell line to generate a stable murine cell line expressing the human EGFR (hEGFR)." (PMID 36139440, 2022). "In head and neck carcinoma, STATs are initiated through a variety of signal transduction pathways, including epidermal growth factor receptor (EGFR), erythropoietin receptors and interleukin (IL) receptor pathways." (PMID 35169188, 2022). "EGFR has been studied as a potential target in various solid cancers, including lung, bladder, colon, breast, and head and neck carcinomas." (PMID 36338727, 2022). "Dr. Eben Rosenthal from Stanford University School of Medicine discussed clinical studies evaluating the use of fluorescently labeled anti-EGFR antibodies in the detection of primary tumor and lymph nodes in head and neck cancer." (PMID 34002555, 2021). "Erlotinib is the inhibitor of epidermal growth factor receptor (EGFR), which is highly over-expressed in many types of solid tumors, e.g., breast, ovarian, lung, colorectal, or head and neck cancers." (PMID 34572928, 2021). "Researchers also found that anti-EGFR Targeted agents can modulate the antitumor immunity in head and neck cancer, showing the close relationship between cancer immunity and anti-EGFR agents." (PMID 34976847, 2021).
head and neck cancer (continued). "Currently, a global phase III clinical trial of NIR-PIT for inoperable head and neck cancer patients is currently underway using an anti-epidermal growth factor receptor (EGFR)-antibody IRDye700DX (IR700) conjugate." (PMID 34064074, 2021). "Currently, the treatment for head and neck cancer mainly involves surgical eradication, radiotherapy (RT), chemotherapy (CT), and epidermal growth factor receptor (EGFR)-targeted drug cetuximab for both HPV(+) and HPV(−) subtypes." (PMID 35198565, 2021). "Given fundamental similarities and overlaps between epithelial cancer types such as breast and head and neck cancers, one would expect that targeting the EGFR/HIF-1/NOTCH axis." (PMID 34944837, 2021). "Anti-EGFR Targeted agents were found to be capable of modulating the antitumor immunity in head and neck cancer and become more and more frequently used in the treatment of nasopharyngeal carcinoma(NPC)." (PMID 34976847, 2021). "This study combined two novel nanomedicines, a novel LCP Pyro PA photodynamic therapy (PDT) and LCP EGFR siRNA gene therapy, to treat head and neck cancer." (PMID 34575510, 2021). "The photo-activating chemical includes an antibody that combines tumor cells (EGFR antibody in head and neck cancers) and a photo-absorbing dye, and the absorption of the NIR light induces a ligand-release reaction and even an antitumor immune reaction." (PMID 35006440, 2021). "Currently, a global Phase 3 clinical trial using an antibody against epidermal growth factor receptor (EGFR) conjugated to IR700 molecule (Cetuximab-IR700) is being tested in patients with recurrent head and neck cancers." (PMID 36405499, 2021). "Cetuximab, an EGFR monoclonal antibody, was infused 5240 times in 249 patients with colon, oral, or head and neck cancers." (PMID 34505396, 2021). "Overexpression of the epidermal growth factor receptor (EGFR) drove the high binding of anti-EGFR antibody-conjugated nanoparticles towards head and neck cancer cells." (PMID 35423427, 2021). "Although targeted therapies such as EGFR inhibitors and immune checkpoint inhibitors have been approved as treatments for head and neck cancers, some patients are resistant to these therapies, and thus the searching for new molecular targets continues." (PMID 35006440, 2021). "Further reduction in EGFR signaling is supported by a recent study that revealed inhibition of N-glycosylation by tunicamycin in head and neck cancer cells inhibited tumorigenesis by triggering endoplasmic reticulum (ER) stress." (PMID 32260356, 2020). "In head and neck cancer, 83% of tumors show overexpression of the epidermal growth factor receptor (EGFR), which is commonly used as a target for various targeted therapies." (PMID 32089747, 2020). "Targeting EGFR and the β1 integrin receptor efficiently induced radiosensitization in head and neck cancers." (PMID 32963499, 2020). "PET imaging with 89Zr-cetuximab presented a difference in the EGFR expression in patients with head-and-neck cancers and in those with advanced colorectal cancers, as revealed by the standardized uptake value (SUV)." (PMID 32560337, 2020). "The Epidermal Growth Factor Receptor (EGFR) proto-oncogene has proven to be a valuable target in multiple types of cancer, including colorectal, lung, and head and neck cancer." (PMID 33153459, 2020). "In particular for EGFR, our previous research has shown that organoids grown from tumors of patients with head and neck cancers possess low/moderate EGFR levels, compared to cell lines traditionally used in EGFR research (e.g., A431 cell line)." (PMID 32977602, 2020).